PIK3AP1 (phosphoinositide-3-kinase adaptor protein 1)
Description:
Signaling adapter that contributes to B-cell development by linking B-cell receptor (BCR) signaling to the phosphoinositide 3-kinase (PI3K)-Akt signaling pathway. Has a complementary role to the BCR coreceptor CD19, coupling BCR and PI3K activation by providing a docking site for the PI3K subunit PIK3R1. Alternatively, links Toll-like receptor (TLR) signaling to PI3K activation, a process preventing excessive inflammatory cytokine production. Also involved in the activation of PI3K in natural killer cells. May be involved in the survival of mature B-cells via activation of REL.
Synonyms: BCAP; FLJ35564
Tractability: Small molecule: a structure with a bound ligand is known. Antibody: its Gene Ontology location is reachable by antibodies, with high confidence; UniProt places it where antibodies can reach, with medium confidence; the Human Protein Atlas places it where antibodies can reach. PROTAC: ubiquitination databases record sites on it; its protein half-life has been measured.
Gene: Protein-coding gene on chromosome 10 (96,593,043 to 96,720,534, reverse strand). Ensembl gene ENSG00000155629.
Subcellular location: Cytoplasm; Cell membrane
Subcellular location (Human Protein Atlas): Cytosol; Nucleoplasm; Plasma membrane
Pathways (Reactome):
Signal Transduction: PI5P, PP2A and IER3 Regulate PI3K/AKT Signaling; PIP3 activates AKT signaling
Disease: Constitutive Signaling by Aberrant PI3K in Cancer
Immune System: Antigen activates B Cell Receptor (BCR) leading to generation of second messengers
Gene Ontology:
Molecular function: protein binding; phosphatidylinositol 3-kinase regulatory subunit binding; signaling receptor binding; identical protein binding
Biological process: positive regulation of phosphatidylinositol 3-kinase/protein kinase B signal transduction; regulation of inflammatory response; toll-like receptor 2 signaling pathway; toll-like receptor 4 signaling pathway; toll-like receptor 7 signaling pathway; toll-like receptor 9 signaling pathway; signal transduction
Cellular component: cytosol; membrane; plasma membrane; cytoplasm
Genetic constraint (gnomAD): Loss-of-function variants: 20 observed, 85.38 expected, observed/expected ratio (o/e) 0.23, 90% interval 0.16 to 0.34. The upper end of that interval is the gene's LOEUF score, 0.34, which puts it in group 1 of 6, group 1 being the genes least tolerant of losing a copy. Missense variants: 820 observed, 1,067.6 expected, observed/expected ratio (o/e) 0.77, 90% interval 0.72 to 0.81. Synonymous variants: 397 observed, 418.14 expected, observed/expected ratio (o/e) 0.95, 90% interval 0.87 to 1.03.
Homologues: Orthologues: chimpanzee PIK3AP1 (99% identical), macaque PIK3AP1 (97% identical), dog PIK3AP1 (92% identical), pig PIK3AP1 (91% identical), guinea pig PIK3AP1 (88% identical), rat Pik3ap1 (86% identical), mouse Pik3ap1 (85% identical), rabbit PIK3AP1 (71% identical), tropical clawed frog pik3ap1 (54% identical), zebrafish pik3ap1 (39% identical), Drosophila melanogaster stumps (19% identical). Paralogues in human: BANK1 (24% identical).
Diseases named in the same sentence as PIK3AP1 in open-access papers:
PIK3AP1 is named in the same sentence as 29 diseases in open-access papers, as found by Europe PMC text mining. Sharing a sentence is not in itself a finding about the gene and the disease. The quoted sentences say what the papers report.
thyroid cancer (4 papers, 2022 to 2023). "We confirmed that miR-1246 affects the signaling pathway of PI3K/AKT via targeting PIK3AP1 and inhibits the development of thyroid cancer." (PMID 34870753, 2022). "miR-1246 hinders the proliferation and the growth of tumors related to the thyroid cancer cells in vivo through regulating PIK3AP1 and inhibiting the signaling of PI3K/AKT." (PMID 34870753, 2022). "Meanwhile, PIK3AP1 upregulation was noted in thyroid cancer samples compared with healthy human tissue samples in the TCGA-THCA dataset." (PMID 34870753, 2022). "The results confirmed that miR-1246 regulates PI3K/AKT signal transduction by targeting PIK3AP1, thus affecting the proliferation of thyroid cancer cells." (PMID 34870753, 2022). "Previous mechanistic data has shown that PIK3AP1 expression drives AKT phosphorylation in gastric and thyroid cancer models, suggesting an oncogenic role of this gene in other cancers." (PMID 36366450, 2022). "Previous studies have shown that PIK3AP1, a therapeutic target, inhibits the occurrence and development of gastric cancer, thyroid cancer, cervical cancer, and others by regulating the PI3K/Akt signaling pathway indicating that PIK3AP1 plays a key role in PI3K/Akt signaling." (PMID 37644011, 2023).
Autoimmunity (3 papers, 2013 to 2022). The occurrence of an immune reaction against the organism's own cells or tissues. "Differential methylation of genes PIK3AP1 and SPON2 is not reported in association with other similar autoinflammatory diseases; however, PIK3AP1 was associated with autoimmunity, and its increased expression was shown to promote TLR7-driven lupus-like disease." (PMID 32793186, 2020). "On the other hand, PIK3AP1 was selected because 70% of infected animals had antibodies to PIK3AP1 peptides, and its relevance has been noted in autoimmunity." (PMID 36101433, 2022).
breast cancer (3 papers, 2018 to 2021). A primary or metastatic malignant neoplasm involving the breast. "Analysis of the TCGA database showed that the expression of genes HPSE, PIK3AP1, SIGLEC7, LAIR1, and CTSL have positive correlations according to the breast cancer subtypes." (PMID 33053017, 2020). "PIK3AP1 (phosphoinositide-3-kinase adaptor protein 1), also known as BCAP, is involved in the phosphatidylinositol 3-kinase (PI3K) pathway and genome wide association studies suggest that the PIK3AP1 gene region might be involved in breast cancer predisposition." (PMID 29854292, 2018).
cervical cancer (3 papers, 2023 to 2025). A primary or metastatic malignant neoplasm involving the cervix. "The epigenetic adjustment of miR-142-5p inactivated the PI3K/AKT signaling pathway by targeting PIK3AP1 and inhibiting cervical cancer progression." (PMID 37397007, 2023). "The lncRNA wilms tumor 1 antisense RNA overexpression could inhibit cervical cancer progression by suppressing phosphoinositide-3-kinase adaptor protein 1 (PIK3AP1) via recruitment of SPI1." (PMID 41299786, 2025).
COVID-19 (2 papers, 2022 to 2024). A disease caused by infection with severe acute respiratory syndrome coronavirus 2. "ILC1s, ILC2s and ILCps in COVID-19 patients also downregulated the gene PIK3AP1 (adj.p= 1.4e-14, 3.5e-16 and 2.7e-06, respectively), which encodes a signaling adapter protein linking the phosphoinositide 3-kinase (PI3K) signaling pathway to various coreceptors." (PMID 39026668, 2024). "The proteins overlapping with the enriched “B-cell Receptor Signaling Pathway (WP23),” JUN, HCLS1, PIK3AP1, and CRKL, were all increased in abundance in the COVID-19 spleen tissue, in addition to IL-18R1." (PMID 34710339, 2022). "Interestingly in ILC1 cells, ICAM1, PIK3AP1, STAT5A, TGFB1 and FAM65B genes show the highest degree of network rewiring across healthy vs COVID-19 correlation networks." (PMID 39026668, 2024).
PFAPA syndrome (2 papers, 2020 to 2025). An auto inflammatory syndrome characterized by recurrent febrile episodes associated with aphthous stomatitis, pharyngitis and cervical adenitis. "Epigenetic changes such as differences in methylation of Phosphoinositide-3-Kinase Adaptor Protein 1 (PIK3AP1) and spondin 2 (SPON2) gene could also be associated with the pathogenesis of PFAPA syndrome." (PMID 40310068, 2025).
acute lymphoblastic leukemia (1 paper, 2021). Leukemia with an acute onset, characterized by the presence of lymphoblasts in the bone marrow and the peripheral blood. "A genomic profiling study has demonstrated PIK3AP1 deletions in acute lymphoblastic leukemia cells." (PMID 33921415, 2021).
adenovirus infection (1 paper, 2022). "The PI3K-AKT signaling pathway (PIK3AP1, PIK3CB, and PIK3R5) is closely related to adenovirus infection and specifically involves mediation of PI3K activation." (PMID 35774982, 2022).
autoimmune myocarditis (1 paper, 2022). Autoimmune myocarditis is an autoimmune disease that affects the heart. "To further investigate whether tissue damage is critical for producing COA4 and PIK3AP1 antibodies, we used the autoimmune myocarditis models induced with Myhc-α 334–352 or SERCA2a 971–990." (PMID 36101433, 2022).
brain glioma (1 paper, 2021). A malignant glioma that involves the brain. "Although the role of this protein in brain gliomas is still insufficiently investigated, recent research performed on cell culture of macrophages and B lymphocytes shows hyperphosphorylation of the PIK3AP1 protein, which enables the activation of PI3K-AKT signaling." (PMID 34209611, 2021).
Burkitt lymphoma (1 paper, 2015). A rare form of malignant mature B-cell non-Hodgkin lymphoma. "These corroborated the upregulation of PIK3AP1 and AKT activation in BJAB cells expressing high levels of both EBERs and EBNA1 (a surrogate of Burkitt’s lymphoma EBV latency I) relative to those expressing only EBNA1." (PMID 26121143, 2015).
glioma (1 paper, 2021). A benign or malignant brain and spinal cord tumor that arises from glial cells (astrocytes, oligodendrocytes, ependymal cells). "Data on CNA show that genes AKT2, AKT3, CHUK, EGFR, PIK3AP1, and PTEN show an increase in copy number alterations with the increased glioma grade." (PMID 34209611, 2021). "Lower grade gliomas, the AA group, harbored the highest number of CNA in genes PTEN (50%), PIK3AP1 (49%), and CHUK (49%), while the DA group carried the highest number of CNA in genes AKT1 (15%), AKT2 (11%), and GSK3β (11%)." (PMID 34209611, 2021). "Our investigation on 751 gliomas showed genetic changes of PTEN in 76%, PIK3AP1 and CHUK in 75%, and EGFR in 74% of the total samples." (PMID 34209611, 2021). "The Kruskal–Wallis test confirmed a significant difference in methylation of all examined genes between glioma types (p < 0.001 for AKT1, AKT3, CHUK, GSK3β, EGFR, PTEN, PIK3AP1; p = 0.032 for AKT2)." (PMID 34209611, 2021). "Recent studies showed an essential role of CHUK protein product (IKK) in glioma tumorigenesis, while PIK3AP1 acts as a negative regulator of toll-like receptor-induced inflammation." (PMID 34209611, 2021).
infantile spasms (1 paper, 2019). A rare epilepsy syndrome characterized by onset of epileptic spasms in infants between 2 and 12 months of age, and rarely up to 24 months. "To date, only two de novo missense variants in PIK3AP1 have been reported in two independent patients with infantile spasms." (PMID 30552426, 2019).
myocarditis (1 paper, 2022). Myocarditis is a condition that is characterized by inflammation of the heart muscle (myocardium). "Similarly, anti-PIK3AP1 antibodies may also have a role in the development of myocarditis, since PIK3AP1 functions as an adaptor protein involving the PI3K signaling pathway, and PIK3AP1 has been reported to have a role in SLE." (PMID 36101433, 2022).
neuroblastoma (1 paper, 2020). Neuroblastoma (NB) is the most common solid, extracranial childhood tumor. "Changed methylation of PIK3AP1 is associated with neuroblastoma, and its upregulation is associated with Waldenström macroglobulinemia." (PMID 32793186, 2020).
Obesity (1 paper, 2024). Accumulation of substantial excess body fat. "Potential associations of PIK3AP1 gene expression in SAT with obesity related traits were examined using previously published microarray and RNA sequencing data." (PMID 39002385, 2024). "Further supporting this, PIK3AP1 gene expression in SAT correlated with obesity related traits." (PMID 39002385, 2024).
prostate carcinoma (1 paper, 2013). A carcinoma that arises from epithelial cells of the prostate gland. "The authors examined the association between several SNPs in PI3Ks genes (PIK3CD, PIK3C2A, PIK3R3, PIK3AP1, and PIK3C2B) and prostate cancer risk: among the five genes, only PIK3C2B showed a cluster of SNPs related to prostate cancer risk." (PMID 23658859, 2013).
tumor (8 papers, 2018 to 2023). "In GBM, differential expression of LYZ and PIK3AP1 alters the immune and tumor microenvironment leading to worse prognoses." (PMID 37189838, 2023). "The PI3K/AKT/mTOR activity, under the regulation of PIK3AP1, regulates T-cell homeostasis, as well as tumor survival and metabolic adaptation." (PMID 38223508, 2023). "Among the top genes in the list, PIK3AP1 encodes a Toll-like receptor (TLR) signaling adapter crucial for linking TLRs to phosphoinositide-3-kinase (PI3K) activation and regulating tumor inflammatory responses." (PMID 34116262, 2021). "MiR-567 by targeting PIK3AP1 could inhibit tumor growth and reverse chemoresistance in GC cells via the PI3K/Akt signaling pathway." (PMID 33954114, 2021). "The results of this integrative cBioPortal analysis suggest that genes AKT3, CHUK and PTEN behave like tumor suppressors, while AKT1, AKT2, EGFR, and PIK3AP1 show oncogenic behavior and are involved in enhanced activity of the EGFR-PI3K-AKT-mTOR signaling pathway." (PMID 34209611, 2021).
cancer (6 papers, 2018 to 2025). A tumor composed of atypical neoplastic, often pleomorphic cells that invade other tissues. "The top-ranked pathways associated with cancer and cell proliferation are highly enriched with the DEGs, such as PIK3AP1, LABM3, AKT1, MYB in “PI3K-AKT pathway” (32%) and “pathways in cancer” (20%)." (PMID 36075900, 2022). "Other cancer causing candidates were SMURF2, PIK3AP1, RSBN1, TTN and SEMA6D, which were ranked in the top 25% potential drivers in transposon insertional mutagenesis studies in mice." (PMID 29854292, 2018). "PIK3AP1 is highly expressed in most cancers, which activates the PI3K/Akt pathway." (PMID 37644011, 2023). "For example, Pik3ap1 displayed preferential loss of signal in the proximal 3′UTR in APC and APN cancer subtypes, uniform degradation in LPC cancer subtype, and no change in mature B cells." (PMID 34594359, 2021).
infection (2 papers, 2020 to 2022). The state of being infected such as from the introduction of a foreign agent such as serum, vaccine, antigenic substance or organism. "Together, our data suggested that CVB3 infection leads to the production of autoantibodies to COA4 and PIK3AP1 but raised a question whether such reactivity could be seen in infections caused by other CVB serotypes." (PMID 36101433, 2022). "There is evidence of infection-induced hypermethylation of PIK3AP1 promoter and downregulation of its expression and evidence of hypomethylation and increased expression of PIK3AP1 triggered by low levels of folic acid." (PMID 32793186, 2020). "To determine whether COA4- and PIK3AP1-reactive antibodies are specific to CVB3 or whether their production can be expected in other serotype infections, we used sera from CVB4-infected mice for ELISA." (PMID 36101433, 2022). "Sera collected from infected or naïve animals on day 21 post-infection were analyzed for their reactivity to COA4 and PIK3AP1, with CVB3 VP1 and KLH as controls." (PMID 36101433, 2022). "We hypothesize that the higher methylation found in the second intron of PIK3AP1 in PFAPA patients could lead to lower expression of the BCAP protein and cause a disrupted inhibition of inflammation, leading to exaggerated inflammation or response to environmental stimuli (for example an infection)." (PMID 32793186, 2020). "Given these similarities, we believe that the pathogenetic pathways for the induction of IgG2a antibodies for COA4 and PIK3AP1 may be similar in CVB3 and CVB4 infections." (PMID 36101433, 2022).
prostate (1 paper, 2022). "Similarly to SMARCD1, we found that numerous downstream targets of SMARCD2 (e.g., PTGR1, TRMP8, PGC) and SMARCD3 (e.g., EGF, PIK3AP1, HSD3B1) were AR-driven genes that are involved in prostate tumorigenesis, progression and metastasis." (PMID 36611918, 2022).
PIK3AP1 also shares sentences with these, for which no sentence is quoted: gastric cancer (2 papers); Sepsis (2); Adenitis (1); brucellosis (1); neurodevelopmental disorder (1); pharyngitis (1); systemic lupus erythematosus (1); Waldenström macroglobulinemia (1).